NEDD4 (NEDD4 E3 ubiquitin protein ligase)
Description:
E3 ubiquitin-protein ligase which accepts ubiquitin from an E2 ubiquitin-conjugating enzyme in the form of a thioester and then directly transfers the ubiquitin to targeted substrates. Specifically ubiquitinates 'Lys-63' in target proteins. Involved in the pathway leading to the degradation of VEGFR-2/KDFR, independently of its ubiquitin-ligase activity. Monoubiquitinates IGF1R at multiple sites, thus leading to receptor internalization and degradation in lysosomes (By similarity). Ubiquitinates FGFR1, leading to receptor internalization and degradation in lysosomes. Promotes ubiquitination of RAPGEF2. According to PubMed:18562292 the direct link between NEDD4 and PTEN regulation through polyubiquitination described in PubMed:17218260 is questionable. Involved in ubiquitination of ERBB4 intracellular domain E4ICD (By similarity). Part of a signaling complex composed of NEDD4, RAP2A and TNIK which regulates neuronal dendrite extension and arborization during development (By similarity). Ubiquitinates TNK2 and regulates EGF-induced degradation of EGFR and TNF2. Ubiquitinates BRAT1 and this ubiquitination is enhanced in the presence of NDFIP1. Ubiquitinates DAZAP2, leading to its proteasomal degradation. Ubiquitinates POLR2A. Functions as a platform to recruit USP13 to form an NEDD4-USP13 deubiquitination complex that plays a critical role in cleaving the 'Lys-48'-linked ubiquitin chains of VPS34 and then stabilizing VPS34, thus promoting the formation of autophagosomes. (Microbial infection) Involved in the ubiquitination of Ebola virus protein VP40 which plays a role in viral budding.
Synonyms: KIAA0093; NEDD4-1; RPF1; MGC176705
Tractability: Small molecule: a structure with a bound ligand is known; it has a binding pocket of medium quality. Antibody: its Gene Ontology location is reachable by antibodies, with high confidence; UniProt places it where antibodies can reach, with medium confidence. PROTAC: UniProt records ubiquitination sites on it; ubiquitination databases record sites on it; its protein half-life has been measured; a small molecule that binds it is known.
Target class: Enzyme; Ligase
Gene: Protein-coding gene on chromosome 15 (55,826,917 to 55,993,660, reverse strand). Ensembl gene ENSG00000069869.
Subcellular location: Cytoplasm; Nucleus; Cell membrane
Subcellular location (Human Protein Atlas): Cytosol; Nucleoplasm; Plasma membrane
Pathways (Reactome):
Signal Transduction: Downregulation of ERBB4 signaling; Regulation of PTEN localization; Regulation of PTEN stability and activity
Immune System: Antigen processing: Ubiquitination & Proteasome degradation; ISG15 antiviral mechanism
Gene Ontology:
Molecular function: beta-2 adrenergic receptor binding; channel inhibitor activity; enzyme binding; potassium channel inhibitor activity; proline-rich region binding; protein binding; protein domain specific binding; RNA polymerase binding; sodium channel inhibitor activity; transmembrane transporter binding; ubiquitin binding; ubiquitin protein ligase activity; ubiquitin-protein transferase activity; phosphoserine residue binding; phosphothreonine residue binding; ionotropic glutamate receptor binding
Biological process: cellular response to UV; DNA damage response; formation of structure involved in a symbiotic process; lysosomal transport; negative regulation of potassium ion export across plasma membrane; negative regulation of sodium ion transport; negative regulation of transcription by RNA polymerase II; neuron projection development; nuclear receptor-mediated glucocorticoid signaling pathway; positive regulation of nucleocytoplasmic transport; positive regulation of phosphatidylinositol 3-kinase/protein kinase B signal transduction; positive regulation of protein catabolic process; progesterone receptor signaling pathway; protein targeting to lysosome; protein ubiquitination; receptor catabolic process; receptor internalization; regulation of membrane potential; ubiquitin-dependent protein catabolic process; ubiquitin-dependent protein catabolic process via the multivesicular body sorting pathway; viral budding; negative regulation of vascular endothelial growth factor receptor signaling pathway; neuromuscular junction development; protein K63-linked ubiquitination; regulation of dendrite morphogenesis; and 6 more
Cellular component: cell cortex; chromatin; cytoplasm; cytosol; extracellular exosome; Golgi apparatus; nucleoplasm; nucleus; perinuclear region of cytoplasm; plasma membrane; protein-containing complex; apicolateral plasma membrane; ubiquitin ligase complex; glutamatergic synapse; membrane; postsynaptic cytosol
Genetic constraint (gnomAD): Loss-of-function variants: 65 observed, 93.09 expected, observed/expected ratio (o/e) 0.7, 90% interval 0.57 to 0.86. The upper end of that interval is the gene's LOEUF score, 0.86, which puts it in group 3 of 6, group 1 being the genes least tolerant of losing a copy. Missense variants: 737 observed, 817.94 expected, observed/expected ratio (o/e) 0.9, 90% interval 0.85 to 0.96. Synonymous variants: 231 observed, 271.01 expected, observed/expected ratio (o/e) 0.85, 90% interval 0.76 to 0.95.
Homologues: Orthologues: guinea pig NEDD4 (91% identical), chimpanzee NEDD4 (91% identical), macaque NEDD4 (90% identical), dog NEDD4 (87% identical), pig NEDD4 (87% identical), rabbit NEDD4 (85% identical), mouse Nedd4 (81% identical), rat Nedd4 (75% identical), tropical clawed frog nedd4 (71% identical), zebrafish nedd4a (60% identical). Paralogues in human: NEDD4L (62% identical), WWP1 (33% identical), HECW2 (33% identical), HECW1 (33% identical), WWP2 (33% identical), ITCH (33% identical), HUWE1 (32% identical), SMURF2 (30% identical), SMURF1 (28% identical), UBR5 (26% identical), HACE1 (24% identical), UBE3B (20% identical), and 12 more.
Diseases named in the same sentence as NEDD4 in open-access papers:
NEDD4 is named in the same sentence as 155 diseases in open-access papers, as found by Europe PMC text mining. Sharing a sentence is not in itself a finding about the gene and the disease. The quoted sentences say what the papers report.
breast cancer (27 papers, 2013 to 2025). A primary or metastatic malignant neoplasm involving the breast. "As a biological approach, the association of NEDD4 with ERα in breast cancer cells was also investigated to reveal the biological mechanisms that influenced clinical results." (PMID 36672488, 2023). "In summary, low expression of NEDD4 in HR-positive breast cancer causes the accumulation of ERα, which leads to a favorable response to hormone therapy and prolonged survival." (PMID 36672488, 2023). "Other studies showed that a low expression of NEDD4 was associated with a good prognosis for patients with breast cancer." (PMID 36672488, 2023). "Additionally, the association of NEDD4 with estrogen receptor α in breast cancer cells was also investigated to reveal the biological mechanisms that influenced clinical results." (PMID 36672488, 2023). "NEDD4 is associated with breast cancer progression and predicts a poor prognosis." (PMID 33875644, 2021). "Apart from the increased PIP5Kα expression, it may also be possible that a defect in NEDD4‐mediated PIP5Kα degradation causes such high levels of PIP5Kα protein in breast cancer cells." (PMID 29851245, 2018). "Many studies have shown that NEDD4 plays a significant role in the progression of breast cancer, bladder cancer, and lung cancer." (PMID 39890782, 2025). "NEDD4 is overexpressed in various human malignant tumors, including gastric, colorectal, prostate, lung, liver, and breast cancers." (PMID 39444619, 2024). "NEDD4-dependent degradation accelerates breast cancer cells metastasis, and enhances colorectal cancer cells chemoresistance to 5-fluorouracil." (PMID 39444619, 2024). "Knockdown of NEDD4 in breast cancer cells induced the accumulation of estrogen receptor α and increased sensitivity to hormone therapy." (PMID 36672488, 2023). "The effect of NEDD4 knockdown on HR-positive breast cancer cells was examined using the ERα-positive breast cancer cell line, MCF−7." (PMID 36672488, 2023). "As the expression level of the NEDD4 protein in breast cancer cells was reported to be correlated with that of NEDD4 mRNA, the NEDD4 mRNA level was used as an indicator of the NEDD4 protein level in the present study." (PMID 36672488, 2023). "NEDD4 maintained the characteristics of stem cell in breast cancer and promoted the growth and migration of breast cancer cells." (PMID 37291499, 2023). "Here, we showed that high ERα expression in HR-positive breast cancer cells via NEDD4 knockdown leads to a high sensitivity to hormone therapy." (PMID 36672488, 2023). "Between February 2007 and November 2017, 278 patients with breast cancer whose NEDD4 mRNA expression levels were measured at Fukushima Medical University were enrolled." (PMID 36672488, 2023). "Our clinical and biological approaches suggest that ERα accumulation in HR-positive breast cancer with low NEDD4 expression results in significant sensitivity to aromatase inhibitors and prolongs survival." (PMID 36672488, 2023). "This study is the first to demonstrate that NEDD4 affects the expression of ERα and influences the prognosis of breast cancer patients." (PMID 36672488, 2023). "In a retrospective cohort study, patients with HR-positive HER2-negative breast cancer with low NEDD4 levels had a good outcome." (PMID 36672488, 2023). "In this study, we employed clinical and biological approaches to elucidate the prognostic impact of NEDD4 on HR-positive breast cancer." (PMID 36672488, 2023). "By proteomic analysis using breast cancer cells under the depletion of NEDD4, the alteration of CSCs markers was identified, suggesting the involvement of NEDD4 in the maintenance of CSCs in this type of tumor." (PMID 35205738, 2022). "SERTAD1 has been implicated in the metastatic spread of breast cancer cells by upregulation of the PI3K/AKT signaling cascade, partly via NEDD4-1-mediated PTEN ubiquitination." (PMID 35625886, 2022).
breast cancer (continued). "Its mechanism of action in breast cancer was through the cascade regulations of the two E3 ubiquitin ligases (NEDD4 and SMURF1), which eventually enhanced the ubiquitination modification of HER2 at K716." (PMID 33875644, 2021). "In contrast, NEDD4 reduced the PIP5Kα-dependent PIP2 pool to inhibit breast cancer cell proliferation through the PI3K/Akt pathway." (PMID 33767993, 2021). "NEDD4 downregulation in breast cancer cells elevated HER3 expression and enhance AKT and ERK signaling, resulting in cell proliferation and invasion." (PMID 33767993, 2021). "A study on breast cancer tissue has also revealed the importance of elevated NEDD4 expression in promoting breast cancer cell growth, progression, and poor prognosis." (PMID 34298639, 2021). "As a result, the higher the expression of NEDD4, the more aggressive and the lower the survival rate of the breast cancer." (PMID 33014839, 2020). "In this study, we realized that breast cancer patients with highly expressing NEDD4 show significantly reduced survival rates, specifically in poorly differentiated breast cancer types which are ER-negative breast cancer types, including HER2+ and TNBC." (PMID 33014839, 2020). "Our study is the first to systemically compare NEDD4 expression in breast cancer and normal tissues." (PMID 31856858, 2019). "As for IGF-1R expression, 85% (68/80) of NEDD4-positive staining breast carcinomas were found to stain positive for IGF-1R whereas only 26.5% (18/68) of BC tissue with negative NEDD4 staining stained positive for IGF-1R." (PMID 31856858, 2019). "The purpose of this study was to determine the role of NEDD4 in the promotion of the growth and progression of breast cancer (BC) and to evaluate the clinicopathologic and prognostic significance of NEDD4." (PMID 31856858, 2019). "In the current study, we studied the association between HER3, NEDD4–1, and NRDP1 protein expression, clinicopathological characteristics and clinical outcomes in primary breast cancer, especially in the HER2-amplified subtype." (PMID 30367623, 2018). "Our results indicate that PIP5Kα‐dependent PIP2 production contributes to the activation of PI3K/Akt signalling and breast cancer cell proliferation, which can be impeded by NEDD4, at least partially, through UPS‐mediated PIP5Kα degradation." (PMID 29851245, 2018). "The majority (82.8%) of breast cancers demonstrated NEDD4–1 protein expression - while only a minor proportion (8.3%) of carcinomas expressed NRDP1." (PMID 30367623, 2018). "Only one earlier study clarified the NEDD4–1 protein expression pattern in breast cancer and demonstrated NEDD4–1 expression in 55% of studied cases." (PMID 30367623, 2018). "Based on this study, our results suggest that NEDD4 can act as a suppressor of breast cancer by negatively regulating PIP5Kα." (PMID 29851245, 2018). "We observed comparable expression levels of endogenous NEDD4 protein in the three breast cancer cells." (PMID 29851245, 2018). "We demonstrated that NEDD4–1 protein was predominantly over-expressed in HER2-amplified breast carcinomas; herein, 83% of carcinomas were positive for NEDD4–1." (PMID 30367623, 2018). "As an E3 ligase, NEDD4 is highly expressed in breast cancer, pancreatic cancer, and gastric cancer." (PMID 39890782, 2025). "Breast cancer harbors large amount of NEDD4 copy number amplification." (PMID 37291499, 2023). "NEDD4 accelerates the degradation of ERα and may, therefore, affect the efficacy of hormone therapy and prognosis in HR-positive breast cancer patients." (PMID 36672488, 2023). "NEDD4 expression has been reported to correlated with breast cancer development and worse survival." (PMID 37291499, 2023). "As a clinical approach, we retrospectively evaluated whether the expression level of NEDD4 affected the prognosis of HR-positive breast cancer patients who received neoadjuvant or adjuvant hormone therapy." (PMID 36672488, 2023).
breast cancer (continued). "NEDD4 is shown to be overexpressed in various types of human cancers including gastric cancer, colorectal cancer, breast cancer, non-small-cell lung carcinoma, and hepatocellular carcinoma." (PMID 34458018, 2021). "We assessed the effects of NEDD4 level on the survival rate of breast cancer patients." (PMID 33014839, 2020). "Verma noted that NDRG1 could interfere with the combination between NEDD4 and its substrate in breast cancer." (PMID 31831018, 2019). "Despite the frequent overexpression in breast cancer, the prognostic value of NEDD4–1 remains unclear in the clinical context." (PMID 30367623, 2018). "NRDP1, in turn, is less frequently overexpressed than NEDD4–1 in breast carcinoma." (PMID 30367623, 2018). "Of clinical relevance is our finding that the PS-flippase and evectin-2/Nedd4 E3 ligase were active in an aggressive metastatic breast cancer cell line, which could lead to new drug targets for cancers in which the malignancy depends on YAP function." (PMID 29093443, 2017). "As NEDD4 negatively regulates PTEN stability, NEDD4 could possibly promote cell growth and migration partly through activation of the mTOR/Akt pathway in prostate and breast cancers." (PMID 24657926, 2014). "We evaluated whether the expression level of NEDD4 affected the outcome of breast cancer patients." (PMID 36672488, 2023). "However, a recent report demonstrated that the NEDD4 protein level was significantly increased in breast cancer samples with the downregulated Cx43 expression, indicating that the reduced Cx43 expression may be related to increased NEDD4 expression." (PMID 35350835, 2022). "Therefore, it is suggested that curcumin may induce NEDD4-mediated PAM suppression in HR- breast cancer in a PTEN degradation-independent manner, worthy of further investigation." (PMID 34298639, 2021). "Interestingly, the Kaplan–Meier plotter showed that the survival rate of patients with a higher expression level of NEDD4 was significantly shorter than those of patients with a lower expression only in relatively aggressive and higher stage (grade 3) breast cancer patients." (PMID 33014839, 2020). "However, only a few studies have investigated the role of NEDD4 in breast cancer (BC) and BCSC." (PMID 33014839, 2020). "To investigate whether NEDD4 contributes to low PTEN levels in human breast cancer, we analyzed the expression of these proteins by immunohistochemistry across a large Swedish cohort of breast tumor specimens, and their transcript expression levels by microarrays." (PMID 26276352, 2016). "Consistently, aberrant expression of NEDD4 has been observed in numerous human cancers, including GC, bladder cancer, NSCLC, and breast cancer." (PMID 38200519, 2024). "The two gene sets including Myc_target1 and Myc_target2 are especially enriched in downregulated proteins following NEDD4 knockdown, indicating that the ESC-like features in ER-negative and highly aggressive breast cancers are lost with NEDD4 knockdown." (PMID 33014839, 2020). "The KM plotter revealed that the survival rate of patients with a high expression of NEDD4 was shorter than that of patients with a low expression of NEDD4 in HER2-positive (HER2+) and TNBC, which have been known as relatively aggressive breast cancers." (PMID 33014839, 2020). "Collectively, these results suggest that PIP5Kα is a novel degradative substrate of NEDD4 and that the PIP5Kα‐dependent PIP2 pool contributing to breast cancer cell proliferation through PI3K/Akt activation is negatively controlled by NEDD4." (PMID 29851245, 2018). "The prevalence of immunohistochemically detectable expression profiles of HER3 (n = 177), NEDD4–1 (n = 145), and NRDP1 (n = 145) proteins was studied in primary breast carcinomas on archival formalin-fixed paraffin-embedded (FFPE) samples." (PMID 30367623, 2018). "Next, we studied NEDD4–1 and NRDP1 protein expression in a cohort of HER2-amplified breast carcinomas." (PMID 30367623, 2018).